AFP (alpha fetoprotein)
Diseases named in the same sentence as AFP in open-access papers (continued):
Sharing a sentence is not in itself a finding about the gene and the disease.
tumor (continued). "In all mice with intrahepatic tumor growth of cells the AFP levels and GLuc increased 5 weeks after xenotransplantation." (PMID 21853130, 2011). "Inclusion criteria were: (a) histological diagnosis of HCC and assessment of tumour grade and (b) determination of AFP mRNA status and VEGF levels in the blood before therapy." (PMID 21912636, 2011). "In 1998, the Cancer of the Liver Italian Program (CLIP) investigators proposed the CLIP score that is based on Child-Pugh grading, distribution of tumour(s), alpha-fetoprotein (AFP) level, and portal vein thrombosis." (PMID 21760664, 2011). "In another report, human α-fetoprotein (AFP) enhancer was combined with a housekeeping gene phosphoglycerate kinase-1 (PGK-1) promoter, to augment the activity of the weak tumor-selective AFP promoter." (PMID 21453283, 2011). "The incidence of vascular invasion, intrahepatic metastases/satellite nodules, tumor capsule formation, and serum AFP level, all were similar in the three groups." (PMID 21933440, 2011). "In subcutaneous models the tumor bulk can easily be monitored by tumor volumetry, and AFP level measurements serve as marker of tumor vitality." (PMID 21853130, 2011). "The high p300 expression rate was higher in patients with higher AFP levels (P < 0.0001), larger tumor size (P < 0.0001), tumor multiplicity (P = 0.012), poorer differentiation (P = 0.036) and later stage (P = 0.015)." (PMID 21205329, 2011). "Semi-quantitative RT-PCR showed that RBMY was detected in 35% (23/66) male HCC tumor tissues, which were confirmed by the expression of tumor marker alpha fetoprotein." (PMID 22073224, 2011). "Pelvic examination, thoraco-abdominal computed tomography scan and the serum tumour markers (ßHCG, AFP, LDH and CA125) were normal." (PMID 21435262, 2011). "Elevated serum AFP levels are associated with acute and chronic HCV, toxic liver injury concentrations and correlate with tumor size and decrease or normalize after tumor removal." (PMID 21299910, 2011). "A few recent studies highlighted the potential role of serial AFP screening in the evaluation of treatment response, with the supposition that AFP is indicative of tumor growth and activity." (PMID 22087135, 2011). "During the past 50 years, AFP has been used as a serum tumor marker for HCC, but its function as a probable predictive factor in OLT for HCC has not been established." (PMID 22087135, 2011). "By avoiding a large tumor mass in the spleen through splenectomy, a better correlation of GLuc/AFP levels to tumor load within the liver is achieved." (PMID 21853130, 2011). "Serum tumor markers are very important contributing factors in the diagnosis and management of testicular tumors, including AFP (produced by yolk sac cells) and B-HCG (expression of trophoblasts)." (PMID 29147233, 2011). "In the context of DC-based immunotherapy, AFP has been considered as a candidate antigen to elicit effective tumor rejection but its suppressive activities on DC function have precluded its implementation." (PMID 21235824, 2011). "There are some reports to identify AFP mRNA for detecting isolated tumor cells (ITC) in peripheral blood (PB)." (PMID 22087143, 2011). "Multiple tumours, vascular invasion, preoperative serum alpha-fetoprotein levels, and tumour size are independent predictors of outcome." (PMID 21994867, 2011). "Of the tumor markers, the serum AFP was elevated (4620 ng/ml), and the serum carcinoembryonic antigen and carbohydrate antigen 19-9 were also slightly elevated." (PMID 21554678, 2011). "In summary, our clinicopathologic analysis indicated that the incidence of ME positively correlated with elevated AFP levels and high grades of tumor and that the extent of ME appears to be related only to the tumor grade." (PMID 20731853, 2010). "Serum AFP correlates well with the measurement of tumor size by caliper, weight of excised tumor tissue and ultrasound measurement of tumor volume." (PMID 24281167, 2010).
tumor (continued). "Elevated preoperative AFP levels and preoperative tumor treatment were correlated with higher one-year recurrence rates." (PMID 20862199, 2010). "In this study, we also found that the CIMP status of patients with HCC after LT was closely associated with clinicopathological parameters, such as preoperative AFP level and tumor number." (PMID 20678188, 2010). "The majority of OGCT produce the tumour markers, hCG and/or AFP which can be helpful in the diagnosis and monitoring the response to treatment." (PMID 20587067, 2010). "Other studies suggest that serum AFP level probably reflects the degree of cellular differentiation, and thus, the extent of the tumor invasion." (PMID 20731853, 2010). "To date, several tumor markers have been proposed as complement or substitute for AFP in HCC diagnosis." (PMID 21092242, 2010). "Elevated AFP levels, preoperative treatments, unfulfilled postoperative MC and up-to-seven criteria, poor tumor differentiation, and presence of microvascular invasion were all predictors of lower RFS by univariate analysis." (PMID 20862199, 2010). "With respect to clinical practice this will be particularly valuable in the development of novel tumor markers, with higher sensitivity than Alpha-Fetoprotein (AFP)." (PMID 21119890, 2010). "The induction of an anti-AFP cell-mediated immune response can control tumour growth in animal models." (PMID 20087354, 2010). "The median time of appearance for late relapse was six years, and the main localisation was the retroperitoneum and the lung, following an increase in the level of the tumour marker alpha-fetoprotein (AFP)." (PMID 19830236, 2009). "After these therapies, the level of tumor markers significantly decreased (AFP: 14.4 ng/ml, PIVKA-II: 32 mAU/ml)." (PMID 19128460, 2009). "After a 5-day PEI chemotherapy following the MAKEI 96 protocol of the German Society for Pediatric Oncology and Hematology (GPOH) AFP decreased, but the tumor size increased to 14 × 14 × 20 cm." (PMID 19909520, 2009). "The antrum and pylorus are the common primary sites of tumour and there were AFP levels much higher than normal." (PMID 19674468, 2009). "AFP, γ-GT, tumor differentiation, size, vascular invasion and encapsulation were found to be significant predictors for OS." (PMID 19948069, 2009). "After CT-scan, immunohystochemistry (positive tumor markers: α-fetoprotein-AFP and human chorionic gonadothropin-hCG) and pathohistological diagnostic procedures, the diagnosis of a testicular teratoma was established." (PMID 19893950, 2009). "A number of studies were conducted quantifying the predictive power of clinicopathological parameters, and our results are consistent with previous reports on vascular invasion, AFP level and tumor size in term of hazard ratios." (PMID 19886989, 2009). "Out of these, all 46 patients in whom elevated levels of the tumour marker alpha-fetoprotein were found at the pre-treatment, demonstrated a tumour marker reduction following the treatment and 89% had a greater than 50% decrease." (PMID 22275961, 2008). "Serum tumour markers are also commonly assessed, with alpha-fetoprotein (afp) being measured 95% of the time, and beta–human chorionic gonadotropin (bhcg) levels 100% of the time." (PMID 18769613, 2008). "Alpha-fetoprotein (αFP) is the most frequently raised tumour marker, though frequently αFP, beta human chorionic gonadotrophin (β-hCG) and lactate dehydrogenase (LDH) are all normal." (PMID 21892262, 2008). "Background liver function (Child-Pugh score) was worse and the tumours were more advanced (tumour size, tumour number, alpha-fetoprotein (AFP), and PVTT) in the BSC group than in other groups." (PMID 18349849, 2008). "There were significant differences between the two groups for the measured levels of tumour markers hCGβ, AFP, CgA, and survival as measured from the time of diagnosis, but not for MIB-1 scores." (PMID 18577995, 2008).
tumor (continued). "There were significant differences between the two groups for the measured tumour markers AFP, hCGβ, CgA, MIB-1, and survival as measured from the time of diagnosis." (PMID 18577995, 2008). "Clinical impression of a linkage between high-grade aggressive tumours and a rise in serum AFP and hCGβ levels led us to perform a systematic review of the utility of AFP and hCGβ measurement in our NET patients." (PMID 18577995, 2008). "To this end, we quantified the expression of SLIT-ROBO and AFP genes using cDNAs of 8 tumor-adjacent normal and 35 tumor tissues." (PMID 19114000, 2008). "Pre-treatment work-up includes ultrasound (US) examination, unenhanced and contrast-enhanced CT or magnetic resonance (MR); serum tumour markers, namely alpha-fetoprotein (AFP) and carcinoembryonary antigen (CEA) dosage." (PMID 22275961, 2008). "HCC patients with a high AFP concentration (≥ 400 ng/mL) tend to have greater tumor size, bilobar involvement, massive or diffuse types, portal vein thrombosis, and a lower median survival rate." (PMID 17244360, 2007). "The program consists of checking the tumor markers AFP and DCP every month, performing abdominal ultrasonography every three months, and performing abdominal computed tomography every 6 months." (PMID 17244360, 2007). "The histological diagnosis was poorly differentiated adenocarcinoma, and tumor production of AFP was confirmed by immunohistochemical staining." (PMID 17634124, 2007). "The currently used tumor markers such as PSA, CA125, CEA, and alpha-fetoprotein (AFP), are all examples of useful low abundance circulating cancer biomarkers that probably arise from the tumor and/or the surrounding stroma." (PMID 19662217, 2007). "The half-lives of known tumour biomarkers in the serum are in the order of a few days and several tumour markers, including AFP are known to return towards normal shortly after successful treatment." (PMID 17060939, 2006). "Routine laboratory investigations, including blood glucose levels, and serum levels of tumour markers (alpha-fetoprotein [AFP], carcinoembryonic antigen [CEA], and carbohydrate antigen [Ca19-9]) were within normal limits." (PMID 17118185, 2006). "The two currently applied approaches to early detection are serial estimation of serum alpha fetoprotein (AFP, a serological tumour marker for HCC) and ultrasound examination." (PMID 17060939, 2006). "The tumor markers alpha-fetoprotein (AFP), carcinoembryonic antigen (CEA), CA 19-9, neuron-specific enolase (NSE) and squamous cell carcinoma antigen were within normal limits." (PMID 16643656, 2006). "Between patients with these neoplasms, we found statistically significant survival, age at onset, level of alpha fetoprotein, and an earlier stage of the disease." (PMID 16259635, 2005). "Tumour marker AFP had a much lower weight in the multivariate analysis than tumour markers HCG and LDH." (PMID 15026798, 2004). "Frequency and tumour specificity of the expression in human HCC was thus greater for the MK compared with the AFP gene." (PMID 12966430, 2003). "P-glycoprotein and MRP1 associated, respectively, to low AFP (P=0.026) and high LDH levels (P=0.014), whereas LRP expression associated with high β-hCG levels (P=0.003) and stage IV tumours (P=0.029)." (PMID 12644825, 2003). "In conclusion, PIVKAII and GGTII are useful tumor markers complementary to AFP for the diagnosis of HCC." (PMID 12799630, 2003). "Since then, an increasing number of studies report that PIVKAII is a useful tumour marker complementary to AFP in detecting HCC." (PMID 12799630, 2003). "The allelic losses were compared with biologic indicators of HCC, such as histological grading, tumour stage, size, and AFP serum levels." (PMID 12454776, 2002). "Both studies found that the combination treatment could enhance the near-term efficacy of the tumor and improve serum alpha-fetoprotein levels." (PMID 41517800, 2026). "All serum tumor markers, including AFP, hCG, and LDH, were within normal limits." (PMID 42292176, 2026).
tumor (continued). "Tumor markers (Alpha-fetoprotein [AFP], CA19-9) were within normal limits." (PMID 41466780, 2026). "Follow-up imaging and AFP trends showed marked tumor regression and biochemical improvement." (PMID 41952676, 2026). "VEGFR2-targeted therapy not only inhibited angiogenesis but also suppressed CSCs and activated tumor immunity, and thus it might be effective in AFP-positive advanced HCC after Atezolizumab/Bevacizumab." (PMID 41140754, 2026). "Furthermore, the CTC-ALRI score outperformed conventional factors (AFP, tumor size) and established models (BCLC, TNM, ERASL, SSCLIP, Korean), with areas under the curve of 0.725 and 0.729 for one- and two-year recurrence prediction." (PMID 41919246, 2026). "Clinical factors including tumor size, AFP, and vessel adjacency were collected." (PMID 42306801, 2026). "The cases showed varying intensities of AFP staining in the tumor tissues." (PMID 41717591, 2026). "Additionally, higher values of bilirubin, largest tumor size, AFP, creatinine, and ascites_3 presence (moderate degree of ascites) are associated with positive SHAP values." (PMID 41536859, 2026). "Interaction terms were incorporated to examine whether the prognostic effect of BMI varied across clinically relevant subgroups defined by tumor differentiation, tumor size, tumor number, and alpha-fetoprotein level." (PMID 41976365, 2026). "AFP may train dendritic cells to promote differentiation of naïve T-cells to regulatory T-cells in the tumor microenvironment, which protects the tumor from adaptive immune responses." (PMID 41717591, 2026). "Elevated levels of CEA and CA19-9 were associated with metastasis of lymph nodes and higher tumour stages, while AFP showed no meaningful association with disease characteristics." (PMID 41836492, 2026). "Assessing AFP levels helps evaluate YGJ’s impact on tumor load." (PMID 41517800, 2026). "We found that DC101 inhibited tumor growth in SK-Hep-1 cells, similar to AFP-positive HCC cells." (PMID 41140754, 2026). "The primary strength of this study lies in its demonstration that ATX may be a robust independent predictor of HCC recurrence in patients treated with curative RFA, surpassing the performance of conventional tumor markers, such as AFP and PIVKA‐2." (PMID 41499228, 2026). "For further mass evaluation, serum tumor markers were evaluated including alpha-fetoprotein (AFP), beta-human chorionic gonadotropin (B-HCG), cancer antigen 125 (CA 125), cancer antigen 19-9 (CA 19-9), and cancer antigen 15-3 (CA 15-3), to help differentiate potential etiologies." (PMID 41332961, 2026). "Furthermore, variables related to tumor burden and liver function, namely, largest tumor size, AFP levels, and ascites, also rank among the top predictors of mortality with both methods." (PMID 41536859, 2026). "Indeed, they included MELD components and other factors, such as AFP, largest tumor size, and degree of ascites." (PMID 41536859, 2026). "Several large cohort and multicenter studies have established MTM-HCC as a histologically distinct entity, accounting for approximately 10–20% of HCC cases, with strong correlations to vascular invasion, larger tumor burden, and elevated serum alpha-fetoprotein (AFP) levels." (PMID 41598441, 2026). "Moreover, the observed reductions in tumor biomarkers AFP and CEA are consistent with previous studies showing that polyphenolic grape derivatives improve liver integrity and reduce systemic oxidative stress." (PMID 41228521, 2025). "Additionally, we have tested the effects of AFP and tumor shape irregularity in the overall population." (PMID 39714631, 2025). "However, despite the extremely high serum AFP levels, the AFP expression on tumor cells appeared relatively weak." (PMID 39522069, 2025). "Among them, S2 has the largest tumor volume and the highest AFP, and has the worst prognosis." (PMID 40771801, 2025).
tumor (continued). "However, the use of KLF5 as a new tumor marker was superior to AFP in terms of specificity and sensitivity, with complementary diagnostic value for HCC, especially in patients with low AFP levels." (PMID 40697993, 2025). "Another study from the EurHeCaLT database, analyzing 306 Milan criteria IN and 116 Milan criteria OUT patients, found that an AFP slope >15 ng/mL/month and mRECIST tumor progression were independent predictors of HCC recurrence and post-LT mortality, regardless of the Milan criteria status." (PMID 40361345, 2025). "Only two studies indicated that a surgical margin greater than 5 mm was necessary for improved long-term outcomes, but this benefit was observed only in specific patient subgroups—those with a high alpha-fetoprotein tumor burden score (ATS) and those with an AFP level between 15 and 200 ng/mL." (PMID 40507240, 2025). "By using propensity score matching (PSM) to reduce selection bias and conducting stratified analysis on key prognostic factors including AFP level, tumor diameter, tumor number, MVI and PVTT, we aim to clarify the efficacy of adjuvant therapy in different high-risk recurrence risk subgroups." (PMID 41200181, 2025). "Changes in CD90(+) CTCs, DCP, and AFP also correlated positively with changes in tumor size." (PMID 40940925, 2025). "Importantly, the role of AFP in tumor progression, prognostic prediction, and metastatic potential extends beyond HCC and has been observed in various other cancer types." (PMID 40430002, 2025). "Additionally, the clinicopathological features of patients with KLF5 overexpression were TNM stage, tumor size, alpha fetoprotein (AFP) level, portal vein thrombosis, and HBV infection." (PMID 40697993, 2025). "While routine blood tests did not reveal major abnormalities, targeted investigations based on clinical and radiological findings demonstrated markedly elevated serum tumor markers: β-hCG at 332,456 mIU/mL, alpha-fetoprotein (AFP) <1 ng/mL, and lactate dehydrogenase (LDH) at 742 U/L." (PMID 40656238, 2025). "In this case, an AFP rise due to tumour lysis of a possible NSGCT component cannot be excluded." (PMID 39934683, 2025). "First, while we found associations between cognitive performance and tumor markers (LDH and AFP), the underlying mechanisms remain unclear." (PMID 40526183, 2025). "Tumor markers including AFP and DCP were comparable between the two groups." (PMID 40940915, 2025). "Elevations in AFP levels may indicate adverse outcomes and advanced tumor stage at the time of diagnosis." (PMID 41025044, 2025). "Laboratory tests, including the tumor markers Cancer Antigen 125 (CA-125), Alpha-fetoprotein (AFP), Cancer Antigen 15-3 (CA15-3), and Cancer Antigen 19-9 (CA19-9), were within the normal range, whereas Carcinoembryonic Antigen (CEA) was slightly elevated (8.04 ng/mL)." (PMID 41199837, 2025). "AIFs consist of AFP-derived growth inhibitory peptides (GIPs) and their analogs that, while not binding to the AFP receptor, can enter and affect the enzymatic activity of tumor cells." (PMID 40430002, 2025). "A 64-year-old male patient with multiple HCCs and portal vein invasion was classified as Child–Pugh B. Preoperative tumor markers showed an alpha-fetoprotein (AFP) level of 12,263.96 ng/mL (reference range: <10.0 ng/mL) and carcinoembryonic antigen (CEA) of 16.4 ng/mL (reference range: <10.0 ng/mL)." (PMID 41262442, 2025). "Notably, SERPING1 expression exhibited significant correlations with serum AFP (p < 0.001), tumor size (p = 0.047), and CLIP score (p = 0.002)." (PMID 39474998, 2025). "Tumor markers, including AFP, CA 19-9, and CEA, can be normal." (PMID 40583924, 2025). "Other serum tumor markers, such as AFP, β‐hCG, LDH, CA 15‐3, CA 19‐9, and CEA, have no diagnostic value in ECS." (PMID 40922694, 2025). "The overexpression of AFP reflects more tumor aggressiveness and burden of HCC." (PMID 40221793, 2025).